IL23R (interleukin 23 receptor)
Diseases named in the same sentence as IL23R in open-access papers (continued):
Sharing a sentence is not in itself a finding about the gene and the disease.
tumor (continued). "The aim of this review is to focus on the role of IL-23R in immune genetics and its potential for modulating the natural history of neoplastic disease." (PMID 39796684, 2024). "The findings of the analysis revealed a significant association between the rs1884444 variant in the IL-23R gene and the HER-2 (human epidermal growth factor receptor 2) status as well as tumor size." (PMID 39796684, 2024). "IL-23R has been identified as a key positive regulator of Th17 cell priming and plays an integral role in inflammatory processes contributing to neoplasia." (PMID 39796684, 2024). "We next sought to elucidate the contribution of IL-23R signaling in Treg cells to tumor progression by generating mice in which Il23r was specifically deleted in Treg cells (Foxp3Cre-YFPIl23rfl/fl)." (PMID 38356059, 2024). "In line with previous observations, we found an expansion of effector T cells and Treg cells in the Treg cell-specific Il23r-KO mouse strain in two tumor models." (PMID 38356059, 2024). "To explore the dynamics of Il23r-KO and WT Treg cells, we analyzed tumor-infiltrating and tdLN-derived Treg cells on days 9 and 14 after B16 tumor inoculation." (PMID 38356059, 2024). "The use of three preclinical models of solid cancer in combination with genetic ablation of Il23r in Treg cells revealed that they are responsible for the tumor-promoting effect of IL-23." (PMID 38356059, 2024). "We circumvented this problem using female Foxp3Cre-YFP/+Il23rfl/fl mice, which allowed us to compare Il23r-KO and WT Treg cells within the same tumor." (PMID 38356059, 2024). "The importance of IL-23R in tumor development and its influence on tumor immunity have been well documented in the scientific literature." (PMID 39796684, 2024). "We also found Il23r to be expressed in purified Treg cells from tumors of B16 tumor-bearing Foxp3DTR-GFP mice, whereas those from steady-state lymph nodes (LNs) and tumor-draining LNs (tdLNs) were low in Il23r expression." (PMID 38356059, 2024). "We identified tumor-associated macrophages (TAMs) as the main cellular source of IL-23 and tumor-infiltrating Treg cells as an IL-23 receptor (IL-23R)-expressing cell type." (PMID 38356059, 2024). "Our findings render the IL-23/IL-23R axis a promising therapeutic target for the selective destabilization of tumor-infiltrating eTreg cells for cancer immunotherapy." (PMID 38356059, 2024). "Preclinical models of solid cancer in combination with genetic ablation of IL-23R in Treg cells have demonstrated that this particular cell type plays an essential role in mediating the tumor-promoting effects of IL-23." (PMID 39796684, 2024). "Among these genes, SPINT2, LNX1, FOXA2, and SOSTDC1 were reported to be related to tumor progression, whereas TYROBP, TREM2, IL23R, CSF2RB, TRAF1, and TGFBR1 were closely associated with immune response." (PMID 36611170, 2023). "While these data would be consistent with IL-23R pathway activation in tumor tissue, STAT3 activation can also be mediated by IL-6 or IL-10." (PMID 38375204, 2023). "The expression levels of IL-23R and IL-17 were elevated in the tumor tissue and serum of patients with BC, and these expression levels were associated with a poor prognosis." (PMID 36140470, 2022). "Higher expression levels of IL-23R and IL-17 in tumor tissue and serum were correlated with shortened overall- and disease-free survival, and growth of bladder carcinoma was reduced in IL-17 knockout mice." (PMID 36140470, 2022). "We also measured IL-23 receptor (IL-23R) in the tumor since IL-23R was reported to be elevated after IL-23 treatment 40, and found that its expression was positively correlated with IL-23 expression." (PMID 34093846, 2021). "The levels of IL-23 and IL-23R were found to be significantly higher in breast cancer tissues and positively correlated with the patient’s tumor size, TNM stage and metastasis." (PMID 33418929, 2021).
tumor (continued). "It is worth mentioning that vvDD treatment also significantly increased IL-23R expression in the tumor at day 5 after treatment and in the vvDD-infected cancer cells in vitro, supporting a rational combination of vvDD and cytokine IL-23." (PMID 34093846, 2021). "The interleukin 23 receptor (IL-23R), a proinflammatory cytokine receptor family member, is highly expressed in tumor tissue to induce local inflammation and promote tumor development." (PMID 34412691, 2021). "The expression of IL-12Rβ2 and IL-23R on laryngeal tumor cells mediated crosstalk between the cancer cells and tumor-infiltrating lymphocytes and affected the prognosis of laryngeal cancer patients." (PMID 33418929, 2021). "Conversely, the expression of cytokine receptor-encoding genes IL7R, IFNGR1, IL18R1, and potentially IL23R (p = 0.065), was downregulated in HCC tumor-infiltrating MAIT cells." (PMID 32849590, 2020). "In tumor cells, the IL-23R molecule is present on myeloma cells, follicular lymphoma, acute lymphoblastic leukemia cells, and diffuse large B cell lymphoma cells." (PMID 32102441, 2020). "We analyzed ESCC tumor tissues by immunohistochemical and immunofluorescence staining and found that IL-23, which was highly expressed, co-localized with Oct-4A in IL-23R+ ESCC cells." (PMID 30483821, 2019). "IL-23R signaling in Tregs promote an immunosuppressive phenotype in the tumor environment, which promotes carcinogenesis." (PMID 24586528, 2014). "miR-let-7f binding affects the expression of IL-23R on the cell surface, thus influencing the IL-23/IL-17 pathway and the immunosuppressive function of Tregs in the tumor environment." (PMID 24586528, 2014). "The importance of IL-23R in tumor development and its influence on tumor immunity has been well recognized." (PMID 24586528, 2014). "IL-23R is involved in multiple important biological processes, including Th17 cell-mediated immune response, tumor-promoting pro-inflammatory processes and the failure of the adaptive immune surveillance." (PMID 24278297, 2013). "IL-23 is predominantly produced by antigen-presenting cells in response to microbial or host immune stimuli and is involved in the regulation of immune responses against infections and tumor development through the engagement of the IL-23 receptor (IL-23R)." (PMID 23393581, 2013). "The expression of the IL-23R was determined in a panel of 37 NSCLC normal tumor matched patient tissues." (PMID 23802098, 2013). "In MSS and microsatellite instability tumours, IL23R immunoreactivity correlated with Dukes’ staging and lymph node metastases, whereas nuclear beta-catenin correlated with lymph node metastases only." (PMID 22173670, 2012). "Duplicate analysis of MSS tumour samples revealed only nuclear beta-catenin in 10 of 43 samples and upregulation of IL-23R-immunoreactivity in 27 of 43 samples." (PMID 22173670, 2012). "Additionally, IL-22, which is functionally associated with IL-23R signaling, has been implicated in promoting Sorafenib resistance in HCC through STAT3 activation, leading to enhanced tumor cell survival and decreased apoptosis." (PMID 39921803, 2025). "Alternatively, the use of existing drugs capable of targeting the IL-23/IL-23R axes under tumor conditions may be explored." (PMID 39796684, 2024). "Preclinical studies have reported that interleukin-23 can promote tumour metastasis through up-regulation of angiogenic factors and that interleukin-23 receptor blockade may confer protection against tumour growth." (PMID 38301482, 2024). "Furthermore, IL-23R signaling has the capacity to impede anti-tumor immune responses, inhibiting the activity of cytotoxic T cells and thereby facilitating tumor evasion of immune surveillance." (PMID 39796684, 2024). "The interleukin-23 receptor pairs with the interleukin-12 receptor β-1 subunit to mediate signalling of interleukin-23, a “master regulator” of innate and adaptive immunity and promoter of inflammatory mediators in the tumour microenvironment." (PMID 38301482, 2024).
tumor (continued). "Importantly, Treg-specific ablation of Il23r led to an equally reduced tumor burden, phenocopying the kinetics observed in Il23rdel/del mice, suggesting that Treg cells are the relevant target of IL-23." (PMID 38356059, 2024). "Interestingly, IL-23R expressed by tumor-infiltrating Treg promotes suppressive activity, whereas IL-23R signaling on Treg in the gut impairs suppressive function and results in Treg apoptosis." (PMID 38022530, 2023). "Collectively, these data support the idea that IL-23R signalling in Treg cells may antagonize the normal suppressive function of Treg cells to promote anti-tumor immunity in CRC." (PMID 38375204, 2023). "Finally, analysis of TCGA data and single-cell RNA-seq analysis of a previously published dataset in human sporadic cancer, revealed that IL23R was highly expressed in CRC compared to other cancers and specifically in tumor-associated Treg cells." (PMID 38375204, 2023). "In a sporadic CRC model, targeting IL-23R in Treg cells increased IL-17 production by CD4+ T cells and increased the frequency of pro-inflammatory macrophages that was associated with decreased tumor volume and improved survival." (PMID 38375204, 2023). "Some studies have shown that the IL-12Rβ2 chain or IL-23R exhibited tumor suppressor functions." (PMID 30662466, 2018). "Recent studies also showed the direct antitumor activities of IL-23/IL-23R in human hematologic malignancies, i.e., pediatric acute leukemia, and IL-23 directly dampens tumor growth in vitro and in vivo through the inhibition of tumor cell proliferation and induction of apoptosis." (PMID 23393581, 2013). "These opposing roles of IL-23R signaling on Foxp3 expression in the tumor and gut may reflect differences in the tissue microenvironments or the differentiation state of responding T cells." (PMID 20732640, 2010). "However, the role of the IL-23/IL-23R axis in tumor progression remains poorly understood." (PMID 40297579, 2025). "To gain insight into the potential mechanism by which IL-23R-deficient Treg cells restrict anti-tumor immunity in IAC, we examined whether a numerical difference in Treg cells might drive the observed increase in tumor volume in Il23rΔTreg mice." (PMID 38375204, 2023). "Moreover, previous studies have indicated that IL-23R can promote tumor growth and may decrease immunosurveillance by CD8+ T-cells." (PMID 24586528, 2014). "Interestingly, unlike spleen Treg cells, tumor-associated Treg cells express IL-23R and activates STAT3 in response to IL-23, leading to upregulation of the Treg-specific transcription factor Foxp3 and the immunosuppressive cytokine IL-10." (PMID 20885915, 2010). "Several genes were similarly down-regulated in all T-LGLL, somewhat less markedly in STAT3-mutated cases, e.g. cluster 2 (149 genes, including key receptors like IL23R and KLRB1) and cluster 8 (46 genes, including tumor suppressors like BEND5 and TCEA3)." (PMID 40721648, 2025). "The pro or anti-tumorigenic effects of the IL-23/IL-23R axis are dependent upon the balance of STAT3 signaling within the tumor and the surrounding tumor cell microenvironment." (PMID 39796684, 2024). "On day 9 after tumor inoculation, we observed reduced expression of CTLA-4, KLRG1 and ICOS in Il23r-KO Treg cells." (PMID 38356059, 2024). "PPI network analysis revealed these genes and modules were mainly related to tumor progression (LOXL1, IKBKE, LNX1, FOXA2, FGF17, and FGF2) and immune response (STAT4, IL23R, LTA, ITK, and IL19)." (PMID 36611170, 2023). "Consistent with IL-23 impairing Treg cell function in the intestine, blocking IL-23R signaling specifically in Treg cells in a CAC model increased tumor volume and dysplasia, perhaps by antagonizing anti-tumor immunity." (PMID 38375204, 2023).
tumor (continued). "It has been demonstrated that IL-23 binds to IL-23 receptor (IL-23R) on ILC3s, which promotes the secretion of IL-17, inducing tumor development in the proximal duodenum, probably driven by NCR+ILC3s (IL-23R+Thy1+NKp46+CD3-) as they are expanded." (PMID 36341381, 2022). "Several studies have shown that pro-tumor and/ or anti-tumor functions of IL17 and IL23 are cytokines that necessarily maintain the Th17 phenotype through its receptor IL23R." (PMID 26083022, 2015). "In contrast with the induction of Foxp3+ Treg cells in the periphery, there is evidence that in the tumor microenvironment, STAT3 signaling through IL-23R expression increases Foxp3 and IL-10 expression by Treg cells." (PMID 20732640, 2010). "Compared to healthy Gingiva controls, OSCC tumor resection specimens without (N0) and with (N+) lymph node metastases showed a significantly increased infiltration of IL-23R expressing cells (mean 5 cells/mm2 vs. 127 cells/mm2 and 192 cells/mm2; p ≤ 0.016)." (PMID 40297579, 2025). "To exclude the potential influence of Cre-mediated toxicity, we confirmed reduced tumor growth in the absence of Il23r in Treg cells in Foxp3Cre-YFP and Foxp3Cre-YFPIl23rfl/fl mice." (PMID 38356059, 2024). "The disruption of IL-23R has been observed to result in the increased reactivity of destabilized Tregs to the cytokine IL-12, the production of γ-interferon, and the recruitment of CD8+ T cells that inhibit tumor growth." (PMID 39796684, 2024). "In this cohort we found IL23R expression to be readily detectable in tumor Treg cells but not in circulating Treg cells." (PMID 38375204, 2023). "One limitation of this work is that we did not study the suppressive function of IL-23R signaling in tumor infiltrating Treg cells in human CRC." (PMID 38375204, 2023). "This raises the possibility that IL-23R signaling in Treg cells affects tumor progression rather than initiation in this model." (PMID 38375204, 2023). "The negative expression of IL23R in our data could be interpreted as a protective mechanism against tumor formation and activation of protumor Tregs." (PMID 40149697, 2025). "Interestingly, IL-23R deletion in Treg cells in the AOM/DSS model of CAC increased tumor size and dysplasia but did not affect tumor number." (PMID 38375204, 2023). "IL-23R could lessen immunosurveillance by CD8+ T cells and accelerate tumor proliferation as well." (PMID 24278297, 2013). "In the corresponding tumour samples, the finding was similar, except that two samples had no NAV3 aberrations despite the presence of upregulated IL-23R expression." (PMID 22173670, 2012).
cancer (32 papers, 2012 to 2025). A tumor composed of atypical neoplastic, often pleomorphic cells that invade other tissues. "Several genetic polymorphisms of the IL-23R were shown to be associated with and increased or reduced risk of cancer development." (PMID 40297579, 2025). "Several variants in the IL-23R gene have been identified as predisposing factors in the development of disparate types of cancer in different populations, while other variants appear to be protective factors." (PMID 39796684, 2024). "The possible biological mechanisms underlying the modification of cancer incidence by IL23R rs10889677 need to be explored." (PMID 38810984, 2024). "The C allele of the rs10889677A>C polymorphism in the 3′-untranslated region of IL-23R exhibited an inverse association with the risk of multiple types of cancer, including breast, lung, and nasopharyngeal carcinoma." (PMID 39796684, 2024). "We identified potential novel associations between four inflammatory markers (pro-adrenomedullin, interleukin-23 receptor, prothrombin, and interleukin-1 receptor-like 1) and risk of site-specific cancers." (PMID 38301482, 2024). "Aside from auto-immunity, this cytokine has also been linked to carcinogenesis and polymorphisms in the IL-23R gene are associated with an increased risk for the development of a number of different cancers." (PMID 23802098, 2013). "IL-23R seems to be associated with the development of cancer." (PMID 40297579, 2025). "This duality is reflected in genetic and preclinical data: IL-23R polymorphisms may confer varying cancer risks, and IL-23 deficiency in mice increases susceptibility to certain tumors, likely by impairing immune surveillance and cellular homeostasis." (PMID 41282022, 2025). "Therefore, prospective studies on both cancer incidence and prognosis are warranted to investigate how the IL23R genetic variant affects outcomes differently." (PMID 38810984, 2024). "Several functional variants in the IL23R gene have been reported to impact cancer susceptibility." (PMID 38810984, 2024). "A comprehensive grasp of the mechanisms underlying the IL-23/IL-23R pathway and the capacity to modulate it represent indispensable prerequisites for the formulation of novel therapeutics for the treatment of immune-mediated disorders and cancer." (PMID 39796684, 2024). "Furthermore, genetic studies have revealed the presence of polymorphisms in the genes IL17A / F and IL23R which are associated with inflammatory bowel disease and some cancers such as bladder, breast, uterus and gastric cancer." (PMID 26083022, 2015). "The IL-23R gene, which maps to chromosome 1 (1p31.2∼32.1), GWAS have reported that chromosomal loci from 1p31 to 1p36 were strongly associated with the development of cancers in Asian populations." (PMID 24586528, 2014). "Furthermore, polymorphisms in the IL-23R have been linked to a number of cancers, including gastric, colorectal, oral, esophageal, leukemia, hepatitis B virus (HBV)-related hepatocellular carcinoma, breast, lung, and nasopharyngeal cancer." (PMID 23802098, 2013). "All these findings might explain the observed decrease in cancer susceptibility in the meta-analysis of IL-23R rs10889677 SNP." (PMID 24278297, 2013). "In some recent studies, the IL23R gene was proved to be a susceptibility gene for several cancers." (PMID 23239971, 2012). "The IL-23R rs10889677A>C polymorphism may exert an influence on T-cell proliferation, which in turn gives rise to modifications in the levels of Tregs in vivo and a consequent modification in cancer susceptibility." (PMID 39796684, 2024). "Therefore, it is biologically reasonable that functional IL-23R polymorphisms may play a role in the development of cancer." (PMID 24586528, 2014). "It is suggested that IL-23R serves a function in different types of cancer expansion and progression, including HCC." (PMID 39921803, 2025).